SLC6A20 (solute carrier family 6 member 20)
Diseases named in the same sentence as SLC6A20 in open-access papers (continued):
Sharing a sentence is not in itself a finding about the gene and the disease.
COVID-19 (continued). "Further, based on results from this study and the COVID-19 host genetics initiative and its update, we further highlight several other genes of interest for our COVID-19 severity hypothesis, namely BCL11A, SLC22A31, SLC6A20, SLC2A5 and HBBP1." (PMID 40240424, 2025). "The analysis of the entire group revealed an association between rs17713054 SLC6A20-LZTFL1 and the increased risk of severe COVID-19 course, regardless of sex and age: risk allele A, OR = 1.78, 95% CI = 1.22–2.6, p = 0.003." (PMID 39175753, 2024). "Colocalization analysis found that two genes (SLC6A20 and LZTFL1) may affect the progression of COVID-19." (PMID 37160831, 2023). "The main urine amino acids during COVID-19 include neutral amino acids (e.g., phenylalanine, leucine, tryptophan) and imino acids (e.g., proline), which are transported by B0AT1/SLC6A19 and SIT1/SLC6A20, respectively." (PMID 35705608, 2022). "Finally, two GWAS have identified the loci 3p21.31 (LZTFL1, SLC6A20, CCR9, FYCO1, CXCR6, and XCR1) and 9q34.2 (ABO) with COVID-19 severity." (PMID 33868239, 2021).
respiratory failure (8 papers, 2021 to 2025). The significant impairment of gas exchange within the lungs resulting in hypoxia, hypercarbia, or both, to the extent that organ tissue perfusion is severely compromised. "Different human polymorphisms have an impact on clinical outcomes: sequence changes in ApoE, TLR7, TMEM189-UBE2V1, as well as SLC6A20, LZTFL1, CCR9, FYCO1, CXCR6, XCR1, have been associated with severe disease outcomes as well as respiratory failure." (PMID 35207458, 2022).
iminoglycinuria (6 papers, 2015 to 2025). A metabolic disorder resulting from defective renal tube reabsorption of proline, hydroxyproline and glycine. "According to this seminal study, SLC6A20 gene variants have been later found to contribute to forms of autosomal dominant hyperglycinuria (phenotype MIM number 138500) as well as digenic iminoglycinuria (phenotype MIM number 242600)." (PMID 36245926, 2022). "The previous studies have reported that the mutation of SLC6A20 may cause hyperglycinuria or iminoglycinuria which may lead to nephrolithiasis." (PMID 36820062, 2023). "Lastly, human mutations in SLC6A20, encoding the SLC6A20 protein that can mediate proline transport, have been linked to complex digenic iminoglycinuria (a renal disorder with impaired reabsorption of glycine and imino acids [proline and hydroxyproline]) and hyperglycinuria." (PMID 33428810, 2021). "Mutations in genes (SLC36A2, SLC6A20, and SLC6A18) encoding amino acid transporters are responsible for iminoglycinuria." (PMID 41142409, 2025). "In addition to pathogenic gene variations, also a reduction of expression of SLC6A20 in the kidney might in principle lead to iminoglycinuria." (PMID 36245926, 2022).
Hyperglycinuria (3 papers, 2020 to 2023). An increased concentration of glycine in the urine. "As a conclusion, the heterozygous mutation of SLC6A20 (c.1072T > C) might be contributed to hyperglycinuria and the formation of nephrolithiasis." (PMID 36820062, 2023).
Hirschsprung disease (2 papers, 2019 to 2022). Hirschsprung disease (HSCR) is a congenital intestinal motility disorder that is characterized by signs of intestinal obstruction due to the presence of an aganglionic segment of variable extent in the terminal part of the colon. "Mutations in SLC6A20 have been associated with Hirschsprung’s disease." (PMID 39086962, 2022).
Obesity (2 papers, 2024). Accumulation of substantial excess body fat. "Moreover, it was observed that, besides obesity, the SLC6A20 variant (allele A of rs13062383) can also be associated with T2D development in humans." (PMID 39273582, 2024). "Strong correlations with obesity were revealed for rs17713054 SLC6A20–LZTFL1 and rs7949972 ELF5, whereas the probability of participation of rs9636867 IFNAR2 in T2D development was high." (PMID 39273582, 2024). "In patients with a BMI ≥30, SNP rs17713054 SLC6A20-LZTFL1 was associated with an elevation in Tsp (p = 0.02), while among patients without obesity (BMI <30) rs61882275 ELF5 (p = 0.003) was found to increase Tsp." (PMID 39175753, 2024). "The correlation between rs17713054 SLC6A20-LZTFL1 and obesity is supported by previous research indicating that LZTFL1 may regulate leptin signaling, and participate in the LepRb signaling pathway in the hypothalamus, which controls energy homeostasis." (PMID 39175753, 2024).
viral infection (2 papers, 2022). "SLC6A20 can form heterodimers with ACE2 and BOAT1, able to function as binding sites for SARS-CoV-2 spike glycoproteins likely impacting the ability of ACE2 to mediate viral infection." (PMID 36228008, 2022). "Notably, a heterodimer of ACE2 and either SLC6A19 or SLC6A20 serves as a binding site for the SARS-CoV-2 spike protein, which may facilitate viral infection." (PMID 35910207, 2022).
Aminoaciduria (1 paper, 2025). An increased concentration of an amino acid in the urine. "The review highlighted 9 genes associated with aminoacidurias, including SLC3A1 (rBAT), SLC7A9 (bo,+AT), SLC6A19 (BoAT1), SLC7A7 (y+LAT1), SLC7A6 (y+LAT2), SLC36A2 (PAT-2), SLC6A20 (SIT-1), SLC6A18 (BoAT3), and SLC1A1 (EAAT3)." (PMID 41142409, 2025).
deafness (1 paper, 2022). An inherited or acquired condition characterized by the complete loss of the ability to hear from one or both ears. "Further investigations are necessary in order to define how a possible lack or reduction of SLC6A20 expression could lead to inner ear malformations and HL in POU3F4-related deafness." (PMID 36245926, 2022).
depression (1 paper, 2025). "Interestingly, SLC6A15 was grouped with SLC6A19 and SLC6A20 (that are interacting with ACE2) in a recent review of SLCs, and it has been linked to the hippocampus and depression." (PMID 40667466, 2025).
lung disease (1 paper, 2020). "However, this locus exemplifies how our data provide a foundation to generate testable hypotheses of how risk variants mechanistically contribute to lung disease, in this case that changes in SLC6A20 expression in AT2 cells may impact severity of SARS-CoV-2 infection of the lungs." (PMID 33164753, 2020).
nephrolithiasis (1 paper, 2023). The presence of a calculus in the pelvis of the kidney; this is most often composed of mineral salts and proteins. "The object was to investigate the relationship between nephrolithiasis and SLC6A20 through pedigree genetic analysis." (PMID 36820062, 2023). "A patient with nephrolithiasis was found to have SLC6A20 variation." (PMID 36820062, 2023).
renal tubular disorder (1 paper, 2014). "The human SLC6A20 that is abundantly expressed in much of the gastrointestinal tract has been suggested as a target gene for a renal tubular disorder of iminoaciduria." (PMID 25310821, 2014).
retinal degeneration (1 paper, 2020). Degeneration of the retina. "This hypothesis is reinforced by a recent large-scale Genome Wide Association Study (GWAS), showing that the proline transporter isoform expressed in RPE, SLC6A20 was significantly associated with AMD and by the fact that inborn errors of proline metabolism can result in retinal degeneration." (PMID 32120889, 2020).
sensorineural hearing loss (1 paper, 2022). "It is therefore conceivable that a defective imino acid transport resulting from reduction of expression SLC6A20 in the inner ear as a consequence of POU3F4 loss of function might lead to sensorineural hearing loss, similarly to what was observed in the context of SLC6A20 pathogenic gene variations." (PMID 36245926, 2022).
infection (10 papers, 2021 to 2024). The state of being infected such as from the introduction of a foreign agent such as serum, vaccine, antigenic substance or organism. "For SARS-CoV-2 susceptibility, rs2229207 (TC genotype, allele C) and rs17860118 (allele T) of IFNAR2 increased the risk of infection, but rs139940581 (CT genotype, allele T) of SLC6A20 reduced virus sensitivity." (PMID 36292769, 2022). "Additionally, we identified 10 genomic regions associated with breakthrough infection (SLC6A20, ST6GAL1, MUC16, FUT6, MXI1, MUC4, HMGN2P18-KRTCAP2, NFKBIZ and APOC1), and one with breakthrough severity (APOE)." (PMID 39384777, 2024). "Another recent study reported the existence of at least three independent association signals in the 3p21.31 region, with one at LZTFL1 being more strongly associated with severity of infection, and the other two at SLC6A20 being primarily associated with susceptibility to infection." (PMID 35768520, 2022). "Previous studies like the one leaded by “The COVID19 Host Genetics Initiative” support the notion that some genetic variants, most notably at the ABO and PPP1R15A loci, in addition to SLC6A20 have a direct effect on susceptibility to infection rather than COVID19 severity." (PMID 35937703, 2022).
tumor (4 papers, 2020 to 2026). "On the other hand, SLC6A20, SLC5A1, SLC4A4, and SLC16A10 were positively associated with OS in 3 tumor types." (PMID 37397501, 2023). "Here, we show systematic profiling of SLC6A20 expressionin pan-cancer tumor and healthy samples together with correlationwith SARS-CoV-2 infection genes ACE2, TMPRSS2, and TMPRSS4 and immunefiltration in tumor samples." (PMID 37041751, 2023). "SLC6A20 acted as a protective prognostic factor and should be downregulated in the tumor group; however, in TCGA, the result was the opposite." (PMID 33154194, 2020). "Taken together, these findings indicate that elevated SLC6A20 expression might play a role in immune infiltrationin a variety of human tumor samples." (PMID 37041751, 2023). "Since SLC6A20 expression was detected at the highest level inneutrophils, TGCA pan-cancer tumor samples were further examined usinga TIMER2.0 data set." (PMID 37041751, 2023).
cancer (3 papers, 2019 to 2023). A tumor composed of atypical neoplastic, often pleomorphic cells that invade other tissues. "SLC6A20, known to be regulated by the3p31.21 locus and linked with the severity of COVID-19 disease, wasfurther examined in pan-cancer samples." (PMID 37041751, 2023). "The SLC6A20 interactingprotein TMEM27, an ACE2 homologue, and its pan-cancer expression profilinganalysis suggests the involvement of SLC6A20 in providingincreased susceptibility of COVID-19 disease in cancer patients." (PMID 37041751, 2023). "Given the role of ACE2,TMPRSS2, and TMPRSS4 in providing increased susceptibility to COVID-19in cancer patients, our findings indicate that SLC6A20 might exhibit a similar function." (PMID 37041751, 2023). "The analysis of pan-cancertumor samples in comparison to their normal counterparts exhibitedthe upregulation of SLC6A20 expression in a widearray of cancer types." (PMID 37041751, 2023). "Thesefindings suggest a potential therapeutic intervention strategy for SLC6A20 in cancer patients with the COVID-19 disease." (PMID 37041751, 2023). "Taken together, these results suggest that elevated SLC6A20 levels might be partly responsible for increasedsusceptibility of cancer patients to COVID-19 disease." (PMID 37041751, 2023). "Last, SLC6A20 was found to interactwith an ACE2 homologue protein TMEM27, and TMEM27 was upregulatedin different cancer types along with its being positively correlatedpredominantly with ACE2 and TMPRSS2, which are known SARS-CoV-2-associatedproteins." (PMID 37041751, 2023).
brain disorder (2 papers, 2021 to 2023). A disease affecting the brain or part of the brain. "Further, pharmacologically inhibiting SLC6A20 may contribute to the treatment of brain disorders via an increase in glycine levels in the brain and N-Methyl-D-Aspartate receptors (NMDAR) activity." (PMID 37359008, 2023).
SLC6A20 also shares sentences with these, for which no sentence is quoted: amyotrophic lateral sclerosis (1 paper); breast carcinoma (1); chronic kidney disease (1); ciliopathy (1); cognitive decline (1); colorectal cancer (1); ear malformation (1); enteritis (1); gastric cancer (1); gastrointestinal tumors (1); Hartnup disorder (1); ischemic stroke (1); kidney chromophobe (1); lung adenocarcinoma (1); malignant mesothelioma (1); neurodegenerative disease (1); Parkinson disease (1); pneumonia (1); pulmonary hypertension (1); renal disorder (1); schizophrenia (1); T-cell acute lymphoblastic leukemia (1).